MMP9 (matrix metallopeptidase 9)
Diseases named in the same sentence as MMP9 in open-access papers (continued):
Sharing a sentence is not in itself a finding about the gene and the disease.
cancer (continued). "Depletion of MMP9 has been shown to decrease cancer progression in multiple animal models of cancer." (PMID 31456939, 2019). "Among the various MMPs, two members of the MMP family, MMP-2 and MMP-9, are recognized as the most important factors for cancer cell invasion and metastasis in many types of cancers, including PC." (PMID 30621039, 2019). "Kaplan-Meier survival analysis was conducted by 5-year overall cumulative survival, which revealed that low TIMP-2 or high MMP-9 expression in cancer tissues was correlated with a worse OS in CRC patients (P < 0.001 and P < 0.001, respectively, log-rank test)." (PMID 31293204, 2019). "MMP-9 plays an important role in various aspects of homeostasis and pathogenesis of cancer development and in the mechanism of pain." (PMID 31239855, 2019). "The aberrant expression of VEGF, MMP‐2, and MMP‐9 was closely related to the growth and metastasis of cancer." (PMID 31762993, 2019). "The STAT3 transcription factor induces the expression of matrix metalloproteinase 2 (MMP-2), MMP-9, and epithelial-mesenchymal transition-related genes in promoting cancer cell invasion and metastasis." (PMID 31885639, 2019). "Remarkably, USP22 knockout had pronounced effects on expression of these important cancer-associated gene sets such as c-Myc, E2F, and selected genes including ALDH1A3, CCNE1/G1, E2F6, HOXA1, MMP9, NFKB2, TP63, TPM4, SET7/9 were validated by qRT–PCR." (PMID 31842906, 2019). "Although the detailed underlying mechanism has yet to be clarified, such S-nitrosylation-mediated inhibition of MMP-9 bears a therapeutic potential for cancer." (PMID 31533268, 2019). "Activation of AKT leads to a significant reduction in E-cadherin expression and induction of MMP-9 expression and secretion in cancer cells." (PMID 30845749, 2019). "The MMP9 levels were elevated in metastasized cancer cells in the lungs and liver in a VGLL1-overexpressing NUGC3 xenograft model." (PMID 31816819, 2019). "Matrix metalloproteinase 9 (MMP-9) has an impact on cancer growth due to type IV collagen degradation, a major component of the basement membrane (BM)." (PMID 31143300, 2019). "MMP9 is undetectable in healthy tissue, but during inflammation and cancer it is highly upregulated." (PMID 31275410, 2019). "Multiple GO terms were enriched associated with MMP-1, MMP-2, MMP-9 and VEGF, and they are closely associated with pathways, proteoglycans and microRNAs related to cancer." (PMID 31311559, 2019). "MMP‐2 and MMP‐9 are closely related to the migratory and invasive ability of cancer cells and present in various malignant tumors." (PMID 30653763, 2019). "The p38 MAPK also acted as a negative regulator during angiogenesis and played an important role in inhibiting cell migration and invasion by downregulating MMP-2/MMP-9 secretion in cancer cells." (PMID 31293977, 2019). "Kaplan–Meier DFS and OS curves of the ESCC cancer patients according to the status of MMP9, CK20, CK19, and uPA levels were examined." (PMID 30817615, 2019). "MMP-2 and MMP-9 play an important role in pathophysiological processes such as cell migration, angiogenesis, and the invasion and metastasis of malignant tumors." (PMID 31777578, 2019). "The findings of numerous studies emphasized the importance of changes in expression levels of MMP-2 and MMP-9 at different stages of cancer of the head and neck region, including organ and regional staging." (PMID 31223594, 2019). "By far, the most well studied proteases in cancer include CG, NE, and matrix metalloprotease 9 (MMP-9)." (PMID 31010242, 2019). "Inhibition of Notch1 can significantly reduce the binding ability of NF-kappa B to DNA, and the expression and activity of MMP-2 and MMP-9 are also significantly inhibited, thus reducing the metastasis ability of cancer cells." (PMID 30622441, 2019). "MMP9, a gelatinase, was significantly upregulated in twelve of the fifteen analyzed cancer types (p = 1E-05 to 4E-27)." (PMID 31200666, 2019).
cancer (continued). "In summary, our study demonstrates that UCA1 plays an important regulator of MMP9 and trophoblast invasion, in addition to its role in the cancer development." (PMID 31572567, 2019). "Antioxidants such as N-acetylcysteine (NAC) and catalase are able to prevent the ANE- and arecoline-induced toxic events such as COX-2 expression, PGE2, IL-1α, cytotoxicity etc. as well as MMP-9 secretion of SAS cancer epithelial cells in this study." (PMID 31831717, 2019). "It is known that PTEN is the negative regulator of the PI3K/Akt pathway, and MMP-9 protein which is a key factor of cancer invasion is regulated by the PI3K/Akt signaling pathway." (PMID 31228937, 2019). "It was known that matrix metalloproteinase-9 (MMP-9) played an essential role in cancer invasion and metastasis by degrading native type IV collagen, which usually functioned as a major structural component of basement membranes." (PMID 31275981, 2019). "We found that lower TIMP-2 or/and higher MMP-9 expression in cancer tissues was correlated with poorer overall survival (OS)." (PMID 31293204, 2019). "Other than NE and CG, neutrophil released matrix metalloproteases (MMP) such as MMP-8 and MMP-9 are also found to be involved in ECM remodeling to facilitate cancer progression." (PMID 31010242, 2019). "The antimetastatic properties of API are that it inhibits cancer cell migration and invasion through attenuation of MMP-9 expression in vitro and in vivo." (PMID 31182131, 2019). "For example, hyaluronan-CD44 binding stimulates gelatinase secretion to regulate cancer invasion and MMP9 docks with CD44 to remodel the ECM at the invasive front." (PMID 31380370, 2019). "Several studies in cancer, kidney, and cardiovascular diseases have demonstrated association of NGAL with MMP9 to facilitate ECM remodeling." (PMID 31737648, 2019). "ANE can activate EGFR, and inhibition of EGFR and JAK signaling by PD153035 and AG490 also suppressed the ANE-induced MMP-9 production of SAS cancer cells." (PMID 31831717, 2019). "The expression profile of MMP-9, whose well-appreciated pathologies is the relationship to cancer owing to its role in extracellular matrix remodeling and angiogenesis, was depicted to experience a slight diminution inflicted by CSD." (PMID 31772601, 2019). "Another study demonstrated that miR-520d inhibits c-Myc, Cyclin D1, and MMP9 expression, and their inhibitory role demonstrated the reduction in the proliferation, invasion, and migration of cancer cells." (PMID 31212896, 2019). "MMP-9 expression was significantly elevated in the bone tissue on day 3 after carcinoma cell injection and in the ipsilateral spinal cord on day 7, which was suppressed by YKS administration." (PMID 31239855, 2019). "A Croatian study on a large group of patients (n = 196) revealed high MMP-9 expression in patients with advanced clinical stage, in patients with metastases to the regional lymph nodes, and in patients with relapsed carcinoma." (PMID 31143300, 2019). "Although STAT3 directly activates the transcription of MMP2 and MMP9 in cancer cells, the regulatory mechanisms in alveolar macrophages should be further validated." (PMID 30410547, 2018). "MMP9 activity was increased 3- to 9-fold in 5 and 60- to 65-fold in 2 of 10 cancer samples (p = 0.03, Fisher's Exact Test)." (PMID 29581841, 2018). "In this review, we summarize some recent advances about exploring MMP-9 as a biomarker in different cancers." (PMID 30262739, 2018). "It is well known that MMP-9 is related to the invasiveness and metastasis of a variety of cancer types." (PMID 30105080, 2018). "In this contest, MMP-2 and MMP-9, play a critical role in cancer cell migration and invasion by stimulating the degradation of ECM and their increased expression is associated with disease progression." (PMID 29721201, 2018). "Transient knock-down of Smoothened (Smo), a critical component of the hedgehog signaling pathway, inhibited the expression of MMP2 and MMP9 in CD44-positive cancer cells." (PMID 29747682, 2018).
cancer (continued). "The overexpression of RBP4 stimulated the expression of matrix metalloproteinase MMP-2 and MMP-9, which degraded extracellular matrix and enabled cancer cells migration." (PMID 29642915, 2018). "In this review, some recent advances in exploring MMP-9 as a biomarker in different cancers are summarized, and recent discoveries of novel MMP-9 biosensors are also presented." (PMID 30262739, 2018). "The metalloproteinases MMP7 and MMP9 are overexpressed in NSCLC and other types of cancers and are strongly associated with poor prognosis." (PMID 29631554, 2018). "It has recently been recognized that inflammatory cytokines, such as tumor necrosis factor-α (TNF-α), upregulate the secretion of matrix metalloproteinase-9 (MMP-9) from cancer cells and thereby promote peritoneal dissemination." (PMID 30544870, 2018). "HJD has been suggested in a report to inhibit angiogenesis through suppressing the expression of VEGFA and MMP-9, thus further restraining cancer growth." (PMID 30108661, 2018). "The elevation of NF-κB or c-Jun and c-Fos nuclear translocation eventually up-regulates MMP-9 expression, which is important for cancer cell invasion." (PMID 30401729, 2018). "Some MMPs, including MMP-2 and MMP-9, are produced as inactive pro-enzymes from cancer cells and are then activated by proteolytic cleavage." (PMID 30336548, 2018). "Due to the role of MMP-9 in cancer metastasis, the association between EGFR and MMP-9 is an intriguing target for the investigation of EGFR’s involvement in PCa invasion." (PMID 30134822, 2018). "The present studies support a role for NEDD9 as an enhancer of MMP9 secretion, invadopodia formation and cancer cell invasion." (PMID 29876004, 2018). "The expression level of MMP-2 and MMP-9 increases during the progression of many cancers, such as breast, endometrial and ovarian cancers, which closely correlates with cancer migration and poor prognosis." (PMID 29614094, 2018). "MMP-9 has been thought to be related to cell migration and invasion by degrading the collagen and other matrix thus facilitating the metastasis of cancer cells." (PMID 29642589, 2018). "Because MMP-9 plays an important role in ECM remodeling and membrane protein cleavage, it is found to be widely associated with cancer pathologies." (PMID 30262739, 2018). "The matrix metalloproteinase-2 (MMP-2), MMP-9 and urokinase-PA (u-PA) are responsible for the degradation of extracellular matrix components and play important roles in the process of cancer invasion and metastasis." (PMID 29636641, 2018). "We evaluated the therapeutic potential of targeting the MMP-9/IL-17A axis, which has been ascribed putative pathobiological roles in various types of cancer." (PMID 29983876, 2018). "Prior studies indicate that highly expressed MMP-2 can facilitate the activation of gelatinase MMP-9, contributing to the invasion and metastasis of cancer cells." (PMID 30484490, 2018). "Generally, destruction of the ECM requires the activation of proteolytic enzymes such as MMP-2 and MMP-922, and activation of MMP-2 and MMP-9 promotes cancer invasion and metastasis." (PMID 29712908, 2018). "Matrix metalloproteinase-2 (MMP2) and matrix metalloproteinase-9 (MMP9) are gelatinases of the matrix metalloproteinase family, which play a crucial role in cancer cell growth and migration due to their ability to degrade extracellular matrix proteins." (PMID 29882874, 2018). "MMP-9 is one of the key factors, which promote cancer metastasis and it is also a transcriptional target of AR, commonly present in metastatic PCa." (PMID 30134822, 2018). "The MMP-9 mediated degradation of collagen is one of the most important steps in the development of cancer cell." (PMID 29861465, 2018). "Alternatively, as shown in the reported studies, MMP9 enhance EGFR expression via PI3K/AKT pathways in cancers of the lung, ovaries, breast and brain." (PMID 30134822, 2018).
cancer (continued). "Because our experiments demonstrated that TNF-α potentiated MMP-9 secretion from both mesothelial cells and cancer cells, we next addressed the effect of the exogenous addition of MMP-9 on the invasive behavior of cancer cells." (PMID 30544870, 2018). "Apart from restricting the migration of cancer cells, dasatinib also declined the infiltration of MMP9+ myeloid cells and limited their motility through down-regulation of MMP9." (PMID 29455663, 2018). "MMP9 is known to play an intrinsic role in the invasive growth of cancer cells; therefore, the following experiments were performed with this particular peptidase." (PMID 29844876, 2018). "Both MMP-2 and MMP-9 were reported to degrade the basement membrane (BM), playing a key role in cancer cell invasion and metastasis." (PMID 29419740, 2018). "Based on the ability to induce the EMT process, E2 and CYP were found to promote the migration and invasion of Ishikawa cancer cells and to increase the protein expression of metastasis-related genes, such as Cathepsin D and MMP-9, in the ER-dependent pathway." (PMID 29316692, 2018). "Although MMP-9 has been found to be a potential cancer biomarker in several types of cancer, many improvements are still needed in this research area." (PMID 30262739, 2018). "MMP-9 has been widely found to relate to the pathology of cancers, including but not limited to invasion, metastasis and angiogenesis." (PMID 30262739, 2018). "This review summarizes some recent advances in exploring MMP-9 as a potential biomarker in cancers, and recent discoveries of novel MMP-9 biosensors are also presented." (PMID 30262739, 2018). "MMP-9 promotes cancer development and progression in most cases, and it can also play a suppressive role in cancer progression in some specific cases, such as colitis-associated colon cancer." (PMID 30262739, 2018). "The mRNA expression and protein levels of MMP-2 and MMP-9, critical factors in cancer cell migration, as well as the activity of MMP-9 also decreased or increased with ARP." (PMID 29464048, 2018). "SNPs affecting MMP-9 and IL-6 have been evaluated as predisposing factors for DVT in cancer patients." (PMID 29872658, 2018). "In recent years, there has been much progress in cancer biomarker research about exploring MMP-9 as a biomarker for different types of cancer." (PMID 30262739, 2018). "Upon further dose- and time-dependent exosome transfection experiments validation by qRT-PCR, we found that cancer exosomes induced stronger upregulation of MMP9 and PGAM1 whilst suppressed BBOX1 and EFEMP1, compared to normal exosomes." (PMID 30008265, 2018). "PMNs activated by a TC-CM are a major source of several protumorigenic and angiogenic factors (i.e. VEGF-A, CXCL8/IL-8, and MMP-9) which are known players in cancer-related inflammation." (PMID 29953504, 2018). "In fact, TNF-α has been shown to positively induce MMP9 expression and secretion in various cancer cells to promote their metastatic ability." (PMID 29748481, 2018). "MMP2 and MMP9 use mainly collagen IV as substrate and digest the basement membrane to promote cell invasion in cancer cells." (PMID 29734379, 2018). "MMP-9 (gelatinase-B), member of matrix metalloproteinase (MMPs) increased cancer cell metastasis by degrading denatured collagens (gelatins) and type iv collagen which are the structural components of ECM(extra cellular matrix)." (PMID 29861465, 2018). "Here, we present a novel strategy for developing cancer therapeutics, based on the simultaneous binding and inhibition of both IL-17A and MMP-9." (PMID 29983876, 2018). "Since MMP-9 is an important target for several cancers and some other MMP-9 related diseases, targeting MMP-9 is of very high value." (PMID 30262739, 2018). "Their putative correlation with MMP-9 suggests a synergy between the two key mechanisms of cancer progression: matrix degradation and anti-apoptotic effects." (PMID 30060564, 2018).
cancer (continued). "Using the 95% confidence interval for benign ovary as the upper limit for normal, MMP-9 was increased in 2 of 12 benign samples, and 7 of 10 cancer samples." (PMID 29581841, 2018). "For instance, OPN, upon binding to αvβ3, can activate Rho GTPase via RANKL, subsequently upregulating the expression of CD44 and MMP-9 and resulting in the increased ability for cancer cell movement and metastasis." (PMID 29500465, 2018). "In cancer research, TNF-α was reported to play a role in the progression of cancer by up-regulating the expression of MMP-9 via the activation of ERK1/2, p38, and JNK intracellular signaling pathways." (PMID 29921577, 2018). "Repression of STIP1 expression through siRNA blocked MMP-9 expression and activity in various cancer cells." (PMID 29304094, 2018). "In 5-Aza treated cells, the expression of cancer associated invasive markers was tested (E-Cadherin, N-Cadherin, Vimentin, Twist, MMP-2, and MMP-9)." (PMID 29695771, 2018). "5-FU also inhibited cancer cell migration and invasion by downregulating the expression of MMP-9, mesenchymal marker vimentin and EMT-inducing transcription factor snail and simultaneously upregulating the expression of epithelial marker E-cadherin." (PMID 29587668, 2018). "Firstly and most importantly, to explore the translational application value of MMP-9 as a potential cancer biomarker (or as one biomarker within a biomarker combination) in one specific cancer, systematic high quality evaluations are critical." (PMID 30262739, 2018). "The TNF-α treatment of these cells resulted in the induction of MMP-9 secretion not only from MKN1 carcinoma cells but also from mesothelial cells." (PMID 30544870, 2018). "Biomarkers IL-6 and IL-8, VEGF, MMP-9, MCP-1, IL-11, IGF-1, and Rantes are associated with different stages of cancer." (PMID 28763032, 2017). "Gelatinase B or matrix metalloproteinase-9 (MMP-9) (EC 3.4.24.35) is increased in inflammatory processes and cancer, and is associated with disease progression." (PMID 28369077, 2017). "To further study how PAM inhibits the metastasis of ES2 cells, we checked the expressions of matrix metalloproteinases (MMPs), especially MMP-2 and MMP-9, which are widely reported to directly promote the invasion ability of malignant cancers." (PMID 28729634, 2017). "MMP2 and MMP9 are enzymes important for metastatic cancer cell to invade the basement membrane, and therefore are indicators of metastasis." (PMID 29156719, 2017). "In particular, we evaluated the effects of treatment with Ganoderma lucidum on the release of IL-6, IL-8, MMP-2 and MMP-9 and other inflammatory cytokines promoting cancer." (PMID 28264501, 2017). "Among MMPs, MMP-2, MMP-9 and membrane-type matrix metalloproteinases (MT-MMPs) are believed to play an important role in cancer invasion and metastasis." (PMID 29163852, 2017). "The inhibition of MMP-9 can effectively attenuate cancer metastasis, and at early stages of cancer the inhibition of MMP-9 is essentially efficacy." (PMID 28969037, 2017). "Among all MMPs, MMP9 is unique for being involved in activating several signaling molecules and pathways during inflammation and cancer, despite being inactive in normal tissues." (PMID 29212256, 2017). "Many studies have found that MMPs, in particularly MMP2 and MMP9, are important molecules in cancer tissue remodeling." (PMID 28587210, 2017). "Consistent with anti-metastatic effect, ALT suppressed the expressions of iNOS, COX-2 and MMP-9 which are well known markers of cancer metastasis." (PMID 28740138, 2017). "MMP9 as an important member of znic-dependent endopeptidases family has been considered to be involved in cancer invasion and metastasis via degradation of the extracellular matrix." (PMID 29296214, 2017). "The relative potency with which isothiocyanates inhibited both MMP-9 activity and cancer cell migration showed the following ranking: PEITC>BITC>SFN." (PMID 28969043, 2017).